TBL1XR1 (TBL1X/Y related 1)
Diseases named in the same sentence as TBL1XR1 in open-access papers (continued):
Sharing a sentence is not in itself a finding about the gene and the disease.
cancer (30 papers, 2013 to 2026). A tumor composed of atypical neoplastic, often pleomorphic cells that invade other tissues. "Although TBL1XR1 has been implicated in cancer in bioinformatics analyses, its expression and roles in cardiovascular disease, particularly in CAD, remain unexplored." (PMID 41476864, 2025). "We also revealed a comprehensive overview of the transcript variants of TBL1XR1 and its expression and clinical significance in cancers." (PMID 38347836, 2024). "This review provided a comprehensive overview of TBL1XR1 in tumorigenesis, shedding new light on TBL1XR1 as a promising diagnostic biomarker and druggable target in cancer." (PMID 38347836, 2024). "Recent studies have highlighted that the genetic aberrations of TBL1XR1 in cancers, especially in hematologic tumors, are closely associated with tumorigenesis." (PMID 38347836, 2024). "Transducin (β)-like 1 X-linked receptor 1(TBL1XR1) has been reported to be overexpressed in various human cancers, as well as contributing to carcinogenesis and progression." (PMID 28977891, 2017). "Several studies investigated the association between TBL1XR1 protein expression and clinical outcomes in various cancers." (PMID 28977891, 2017). "More and more studies reported that the expression of TBL1XR1 was associated with both clinical progression and patient survival in various human cancers." (PMID 28977891, 2017). "Hazard ratios (HR) with 95% confidence intervals (CI) were applied to assess the association between TBL1XR1 expression and cancer prognosis." (PMID 28977891, 2017). "Nine of ten studies reported the association between TBL1XR1 and OS, with a total of 1700 cancer patients." (PMID 28977891, 2017). "This suggests that gains in these genes may cause increased expression of NAALADL2 and TBL1XR1 in cancers." (PMID 32796921, 2020). "Rearrangement of TBL1XR1 (3q26.32) have been identified in various cancers involving different genes, including RARA (17q21), HMGA1 (6p21), TP63 (3q28), RET (10q11.2), and PIK3CA (3q26.32)." (PMID 41123735, 2025). "A similar analysis was performed at the mRNA level, revealing BACH2 (9 tissue-specific interactions in COAD) and SLC2A1 and TBL1XR1 (7 interactions in different cancer tissues) as the most recurrent mRNAs." (PMID 41183125, 2025). "Then, we address more detail about the cancer pathways that TBL1XR1 modulates and further elucidate the molecular foundation for TBL1XR1’s potential as a cancer target." (PMID 38347836, 2024). "We made a systematic evolutionary tree of TBL1XR1 that showed the explorations made so far with respect to its relevant researches in cancers." (PMID 38347836, 2024). "The effects of TBL1XR1 on controlling cancer cell proliferation have recently come into focus in new investigations." (PMID 38347836, 2024). "The researches illustrating TBL1XR1’s function in foretelling malignant phenotypes, such as cancer metastasis, have been published." (PMID 38347836, 2024). "Increasing research has shown that TBL1XR1 overexpression in cancer is closely connected to clinical traits." (PMID 38347836, 2024). "Over the past 20 years, the emerging oncogenic function of TBL1XR1 in cancer development has been discovered." (PMID 38347836, 2024). "When taken as a whole, targeting TBL1XR1 is a novel and interesting approach to the detection and treatment of cancer." (PMID 38347836, 2024). "Genetic changes of TBL1XR1 such as gene variations and gene arrangement were present in cancers especially in hematologic tumors including lymphoma and leukemia." (PMID 38347836, 2024). "Comparing each type of ovarian epithelial carcinomas to relatively healthy fallopian tubes, TBL1XR1 was expressed at a relatively upregulated level in both the nucleus and cytoplasm of cancer cells." (PMID 38347836, 2024). "Post-transcriptional and post-translational modification are responsible for the expression and function of TBL1XR1 in cancer." (PMID 38347836, 2024).
cancer (continued). "Based on that, we investigated radiation resistance in NSCLC, mainly focusing on the influence of LINC01578/miR-216b-5p/TBL1XR1 axis on biological functions of radiation-resistant cancer cells." (PMID 35475502, 2022). "The top 10 frequently affected cancer-associated genes are HIRA (OG), CSMD1 (TS), CDH13 (TS), PRRX1 (OG), FHIT (TS), MGAM (OG), TBL1XR1 (OG), RHOA (OG), FGF14 (TS), and CNTNAP2 (TS)." (PMID 35013466, 2022). "Quantitative PCR and immunoblotting showed that TBL1XR1 was up-regulated in cancer tissue samples of patients." (PMID 35475502, 2022). "The mechanism concerning to LINC01578 in radiation resistance in NSCLC is related to miR-216b-5p/TBL1XR1 sequencing, forming a novel lncRNA-miRNA-mRNA interplay in cancer progression." (PMID 35475502, 2022). "This study centred around two genes; NAALADL2 and TBL1XR1, both of which are attractive therapeutic targets with TBL1XR1 previously suggested as a potential cancer target; operating via the TGF-β signalling pathway and potentially regulating AR signalling." (PMID 32796921, 2020). "TBL1XR1 has been generally considered as predictor for prognosis, however, the case was different according to cancer types." (PMID 28977891, 2017). "As a potential predictor and therapeutic target in cancers, TBL1XR1 protein has attracted growing attentions." (PMID 28977891, 2017). "Pooled results revealed that DFS was shorter in cancer patients with elevated TBL1XR1 protein (HR: 1.51, 95 % CI: 1.19–1.84, p < 0.001), without significant heterogeneity among studies (I2=21.5 %, Ph=0.281)." (PMID 28977891, 2017). "Meanwhile, high TBL1XR1 expression level also indicated a shorter five-year OS for cancer patients (HR: 1.70, 95 % CI: 1.40–2.00; p < 0.001)." (PMID 28977891, 2017). "The dysregulated expression of TBL1XR1 was frequently observed in lesions and cancerous tissues, and it was involved in cancer development and metastasis." (PMID 28977891, 2017). "Considerable researches have been carried out to determine the role and mechanism of TBL1XR1 in cancers." (PMID 27672238, 2016). "Different observations have been made regarding the significance of TBL1XR1 in malignant tumors." (PMID 40074836, 2025). "TBL1XR1 was mostly discovered in the nucleus of benign prostate cell line and benign prostatic glands, whereas it was found in both the cytoplasm and nucleus in cancer cells and malignant glands." (PMID 38347836, 2024). "TBL1XR1 was reported to promote cancer metastasis via activating Wnt-β-catenin signaling." (PMID 38347836, 2024). "Considering the complex roles of TBL1XR1 in cancer, a variety of miRNAs may control the activity of various cancer cells by targeting TBL1XR1." (PMID 38347836, 2024). "Additionally, androgen receptor (AR) and progesterone receptor (PR) positive cases had higher levels of TBL1XR1 expression in the nuclear of cancer cells." (PMID 38347836, 2024). "As TBL1XR1 was abnormally expressed in cancers and related with advanced diseases and predicted poor prognosis, TBL1XR1 must have participated in various processes of cancer development and further progression." (PMID 38347836, 2024). "Although its full range of functions and interactions are not known, Tbl1xr1 has been implicated in a variety of cancer types including lymphoma, as well as in a spectrum of neurodevelopmental disorders." (PMID 38378692, 2024). "In conclusion, miRNAs may specifically target and suppress the expression of TBL1XR1, thereby reducing the development of cancer." (PMID 38347836, 2024). "In addition, TBL1XR1 is involved in cancer stem cell maintenance through activation of the MEK and PI3K/Akt pathways with a mechanism that involves the stem cell factor SOX2, also a 3q26 gene." (PMID 34436017, 2021). "The percentage of cancer patients with high TBL1XR1 expression was ranged from 33.80 % to 61.19 %." (PMID 28977891, 2017). "TBL1XR1 overexpression has been observed in diverse cancers." (PMID 28152507, 2017).
cancer (continued). "Our meta-analysis suggested that TBL1XR1 might be served as a novel and promising biomarker to predict prognosis and clinicopathologic characteristic for cancer patients." (PMID 28977891, 2017). "Furthermore, accumulating evidence suggested that TBL1XR1 affected tumorigenesis and cancer progression." (PMID 28977891, 2017). "Several cancer-related signaling pathways have been reported to be activated by TBL1XR1." (PMID 28977891, 2017). "With all these result, it can be seen that the clinical significance of TBL1XR1 was inconclusive or even contradictory, more dedicated-designed studies and trials should be performed before the application of TBL1XR1 as prognosis predictor for a certain cancer type." (PMID 28977891, 2017). "TBL1XR1 is positively correlated with aggressive behavior of tumors and its overexpression might be a crucial factor in the development of various human cancers." (PMID 28977891, 2017). "This synthetic analysis was performed to assess whether TBL1XR1 protein could act as a potential prognostic molecular marker for human cancers." (PMID 28977891, 2017). "All these results suggested that TBL1XR1 might be served as a promising and candidate prognostic marker for human cancers." (PMID 28977891, 2017). "This discrepancy of TBL1XR1 expression may relate with cancer type, TBL1XR1 gene amplification, or focal deletions, suggesting the complex role of TBL1XR1 in cancer progression." (PMID 27672238, 2016). "Multitude of cancer-related signaling cascades like Wnt-β-catenin, PI3K/AKT, ERK, VEGF, NF-κB, STAT3 and gonadal hormone signaling pathways are tightly modulated by TBL1XR1." (PMID 38347836, 2024). "Gene expression correlation analysis in patients’ cancer tissue samples showed that miR-216b-5p was negatively correlated with TBL1XR1 and LINC01578 was positively correlated with TBL1XR1." (PMID 35475502, 2022). "Cancer-related genes commonly amplified from 3q26 include PIK3CA, TBL1XR1, DCUN1D1, SOX2, MECOM, PRKCI, and TERC." (PMID 34436017, 2021). "The lncRNA GPRC5D-AS1 with CNVs driving the dysregulation of downstream cancer genes such as PRKCI, SEM1, TBL1XR1, IMPACT, and RPL22L1 further disturbed the activities of NOTCH signaling pathway that is usually inactivated in LUSC." (PMID 34925461, 2021). "Despite its well‐documented role in cancer, the involvement of TBL1XR1 in cardiovascular disease has not been determined." (PMID 41476864, 2025). "In summary, TBL1XR1-mediated EMT and angiogenesis cooperatively promote cancer metastasis." (PMID 38347836, 2024). "Although cancer and TBL1XR1 neurodevelopmental disorder have not been reported to co-occur, overlapping genetic variants have been reported across both phenotypes." (PMID 38378692, 2024). "The elevated TBL1XR1 could promote lymphangiogenesis and lymphatic metastasis in ESCC via upregulation of VEGF-C, which had close relations with cancer metastasis and prognosis." (PMID 28977891, 2017). "Additionally, ERK1/2 pathway and NF-κB pathway have been reported to be activated by TBL1XR1 in GC and NPC, suggesting that TBL1XR1 played an important role in cancer progression and drug resistance and may act as a new therapeutic target for those cancers." (PMID 28977891, 2017). "Moreover, accumulated studies suggest that TBL1XR1 may play an important role in tumorigenesis, invasion, metastasis, and developing resistance to therapies and has potential to be a negative prognosis biomarker in various cancers." (PMID 27672238, 2016).
neurologic disease (2 papers, 2021 to 2024). "The aim of this current study is to evaluate the phenotypic spectrum and developmental trajectories of patients with TBL1XR1-associated neurologic disease." (PMID 38378692, 2024). "Understanding of the neurologic disease associated with TBL1XR1 is currently limited due to the rare nature of this disorder and the heterogeneity in the range of phenotypes reported." (PMID 38378692, 2024). "It is only recently that TBL1XR1 has been linked to neurologic disease." (PMID 38378692, 2024). "Although significant genetic and phenotypic heterogeneity has been reported in TBL1XR1-related neurologic disease, the effect of genotype on ultimate presentation is not clear." (PMID 38378692, 2024).
hematopoietic neoplasms (1 paper, 2017). "Conversely, hematopoietic neoplasms demonstrate abnormal regulation of TBL1XR1 through chromosome rearrangement and point mutations." (PMID 28152507, 2017).
TBL1XR1 also shares sentences with these, for which no sentence is quoted: acute promyelocytic leukemia (6 papers); neurodevelopmental disorder (3); Angelman syndrome (2); B-cell lymphoma (2); breast tumors (2); invasive breast carcinoma (2); acute kidney injury (1); Aicardi syndrome (1); amyotrophic lateral sclerosis (1); attention deficit-hyperactivity disorder (1); brain malformations (1); cardiovascular disease (1); cholangiocarcinoma (1); Cornelia de Lange syndrome (1); COVID-19 (1); dilated cardiomyopathy (1); fatty liver disease (1); Glucose intolerance (1); gynecological cancers (1); heart failure (1); hemorrhage (1); hypertriglyceridemia (1); infection (1); Insulin resistance (1); ischemic cardiomyopathy (1); Kabuki syndrome (1); learning disability (1); liver cancer (1); microcephaly (1); myeloid leukemia (1).
A further 8 diseases each share a sentence with TBL1XR1 in 1 paper.